CEP290 (centrosomal protein 290)
Diseases named in the same sentence as CEP290 in open-access papers (continued):
Sharing a sentence is not in itself a finding about the gene and the disease.
ciliopathies (81 papers, 2010 to 2025). "There is a high level of programmed frameshifting in cilia-associated genes within the ciliary basal body, including BBS family proteins, CEP290, and δ-/ε- tubulin, which are also closely associated with ciliopathies." (PMID 40432967, 2025). "Centrosomal protein 290 (CEP290), a ciliary protein implicated in ciliopathies, localizes to the ciliary base and the centrosome in ciliated cells." (PMID 40632733, 2025). "Joubert syndrome can be caused by mutations in one of >40 genes, including CEP290, which is one of the most intriguing ciliopathy genes." (PMID 41064933, 2025). "CEP290 is a major ciliopathy-associated gene that encodes a centrosomal and ciliary transition zone protein." (PMID 41064933, 2025). "Mutations in Cep290, a gene related to ciliopathy, result in a wide range of phenotypes, possibly due to the complex interplay between primary ciliary dysfunction and other cellular defects." (PMID 40632733, 2025). "Cilia gene cep290, mutations of which are involved in human ciliopathies, regulates CaCO3 crystallization and functions in otolith formation." (PMID 39857604, 2024). "Additional truncating variants in CEP290 have been linked to various ciliopathies, including JBTS and Bardet–Biedl syndrome." (PMID 39766851, 2024). "Like RPGRIP1L, the human CEP290 gene encodes a TZ protein and its mutation leads to severe neurodevelopmental ciliopathies." (PMID 39388365, 2024). "Mutations in CEP290 are associated with several syndromic ciliopathies, such as Joubert syndrome, Bardet–Biedl syndrome, nephronophthisis, Meckel–Gruber syndrome, and Senior–Loken syndrome." (PMID 38474133, 2024). "CEP290, a widespread ciliopathy-associated gene, can present with a homozygous rd16 mutation that leads to complete photoreceptor degeneration." (PMID 38256083, 2024). "Cep290 encodes a protein involved in cilia function and mutations within it are known to cause a variety of syndromic ciliopathy phenotypes." (PMID 37624784, 2023). "Taken together, this work supports eupatilin as a potential variant-independent approach for CEP290-associated ciliopathies." (PMID 37371046, 2023). "Biallelic variants in the cilia gene CEP290 (NPHP6) can cause a series of syndromic ciliopathies, including Joubert syndrome, nephronophthisis, Meckel–Gruber syndrome and Senior–Loken syndrome." (PMID 37371046, 2023). "In particular, the phenotypes of CEP290-associated ciliopathies are very similar to those in our Crb3 knockout mouse model, with lethality and ocular and renal abnormalities." (PMID 37737843, 2023). "Autosomal-recessive variants in CEP290 (NPHP6) are implicated in an extensive range of syndromic clinical ciliopathies, including LCA, SLS, JBTS, BBS, and MKS and also isolated nephronophthisis." (PMID 37628633, 2023). "It is reported that CEP290 mutations cause a spectrum of ciliopathies from Leber congenital amaurosis type 10 to embryolethal Meckel syndrome." (PMID 36245994, 2022). "CEP290 mutations have been associated with several ciliopathies that vary widely in their severity and clinical manifestations." (PMID 34155518, 2021). "We used the same techniques to examine the effects of CEP290 deficiencies on the localization of ciliary components in mouse ciliopathy models." (PMID 34520396, 2021). "To date, more than 130 mutations in CEP290 have been linked to a spectrum of human ciliopathies, raising the question of how mutations in a single gene can cause so many different disease syndromes." (PMID 34155518, 2021). "Many ciliopathy genes, such as CEP290, IFT140, and IQCB1 initially reported to cause syndromic retinal degeneration, but were later identified as having vital roles in LCA pathogenesis as well." (PMID 33957996, 2021). "Over 130 CEP290 mutations have been linked to a wide spectrum of human ciliopathies, raising the question of how mutations in a single gene cause different disease syndromes." (PMID 34155518, 2021).
ciliopathies (continued). "Mutations in the cilium-associated protein CEP290 cause retinal degeneration as part of multiorgan ciliopathies or as retina-specific diseases." (PMID 34520396, 2021). "In contrast to the human data, a mouse study shows that mutation of the ciliopathy gene Mkks mitigates the severity of Cep290 deficiency." (PMID 33438800, 2020). "While anosmia was originally associated with Bardet-Biedl Syndrome and Leber congenital amaurosis, two known ciliopathies, it is now known to be associated with a subset of ciliopathies that have mutations in Cep290 or KIF17." (PMID 32993148, 2020). "CEP290 is a ciliary gene frequently mutated in ciliopathies, resulting in a broad range of phenotypes, ranging from isolated inherited retinal disorders (IRDs) to severe or lethal syndromes with multisystemic involvement." (PMID 33105651, 2020). "CEP290 mutations are strongly associated with retinal dystrophy and photoreceptor degeneration is one of the most common symptoms of ciliopathies." (PMID 30970040, 2019). "Mutations in CEP290 are associated with numerous syndromic ciliopathies such as Joubert syndrome (JBTS), nephronophthisis (NPHP), Meckel-Gruber syndrome (MKS), and Senior-Loken syndrome (SLSN)." (PMID 27151457, 2016). "Mutations in CEP290 cause other partially overlapping, but distinct, ciliopathies such as JBTS, MKS, NPHP, or SLSN." (PMID 27151457, 2016). "Here, we focus on two ciliopathy genes involved in retinal dystrophy: CEP290, mutations in which cause up to 15 to 25% of LCA; and RPGR, the most common cause of X-linked RP and one of the most frequent causes of all forms of RP." (PMID 23351659, 2012). "Why then is only CEP290 associated with other syndromic ciliopathies even though RPGR is ubiquitously expressed?" (PMID 23351659, 2012). "Based on the human data, a null allele of Cep290 is expected to have a severe, full-spectrum ciliopathy phenotype, which has recently been confirmed in mice (Rachel RA, Yamamoto EA, Dong L, Swaroop A, unpublished data)." (PMID 23351659, 2012). "CEP290 mutations lead to a range of ciliopathy syndromes with variable clinical manifestations in humans." (PMID 23351659, 2012). "Mutations in CEP290, encoding a centrosomal protein essential for ciliary assembly and trafficking, have been associated with several ciliopathies, including Bardet–Biedl syndrome 14 (OMIM 615991), Joubert syndrome (OMIM 610188), and Meckel syndrome type 4 (OMIM 611134)." (PMID 40565534, 2025). "Furthermore, mice deficient in Cep290 develop symptoms consistent with ciliopathies including reduced numbers of primary cilia on renal epithelial cells and the development of kidney cysts." (PMID 40247090, 2025). "We recently showed that eupatilin can be used as a variant-independent approach for human CEP290-associated ciliopathies in retinal organoids, confirming the work of Kim and colleagues who reported a beneficial effect of Eupatilin in rd16 CEP290 mouse model and CEP290null RPE1 cells." (PMID 39934925, 2025). "While RNA antisense oligonucleotides and gene editing are potential treatment options for the common deep intronic variant c.2991+1655A>G in CEP290, there is a need for variant-independent approaches that could be applied to a broader spectrum of ciliopathies." (PMID 37371046, 2023). "Similarly, while targeting CEP290 (NPHP6), a ciliopathy gene linked to BBS, in zebrafish at the mRNA level resulted in severe cilia-related phenotypes, only a mild defect restricted to photoreceptors was observed in genomic mutants." (PMID 35653384, 2022). "Similarly, there distinct genetic mutations in CEP290 (centrosomal-cilia protein 290) displayed in diverse syndromic ciliopathies." (PMID 34233705, 2021). "Yet, it is unclear whether these different ciliopathy-associated mutations affect distinct functions of CEP290 at different locations, or if they form an allelic series impacting the same function." (PMID 32747192, 2021).
ciliopathies (continued). "So far, no clear genotype-phenotype relationship is established for CEP290-associated ciliopathies, though the function of residual CEP290 from hypomorphic alleles may be related to the less severe clinical manifestation." (PMID 32747192, 2021). "Cep290 mutations have been implicated in NPHP6 and a range of other ciliopathies." (PMID 34828368, 2021). "Further experiments inducing full loss of arl13b or unc119b function in a cep290-deficient larvae may show more severe ciliopathy phenotypes." (PMID 34155518, 2021). "Co-immunoprecipitation experiments demonstrated that CCDC66 interacts with numerous proteins that function in ciliogenesis (i.e. CEP72, CEP290 and PCM1) and CEP290 has also been previously implicated in retinal degeneration in human ciliopathies and mouse models." (PMID 33273526, 2020). "Mutations in CEP290 encoding a centrosomal protein important to cilia formation cause a spectrum of diseases, from isolated retinal dystrophies to multivisceral and sometimes embryo–lethal ciliopathies." (PMID 31091803, 2019). "Mutation of CEP290 is a major cause of ciliopathies and non-syndromic retinal degeneration." (PMID 30970040, 2019). "Mutations in CEP290 have been linked to a group of multi-organ disorders - termed ciliopathies." (PMID 30478281, 2018). "We hypothesised that Cep290, which is implicated in several ciliopathies (including MKS and JBTS) and is suggested to be a structural component of the TZ in Chlamydomonas, might represent such a protein." (PMID 26982032, 2016). "Interestingly, it has recently been suggested that increased replication stress, similar to that often seen in cancers due to oncogene activation, is a phenotype associated with a subset of ciliopathies, such as CEP290-associated Joubert syndrome." (PMID 27335639, 2016). "Mutations in CEP290 could cause Joubert syndrome, a heterogenous ciliopathy characterized by cerebellar vermis hypoplasia and severe ID, two clinical findings also typical for TARP syndrome." (PMID 24000153, 2013). "In addition, CP110 has been demonstrated to associate with a human ciliopathy protein, Cep290, (also known as BBS14, NPHP6, JBTS5, SLSN6, MKS4 and LCA10;)." (PMID 24053599, 2013). "Notably, different mutations in CEP290 can disrupt specific module connections to varying degrees, which might explain why CEP290 mutations cause a heterogeneous range of ciliopathy phenotypes." (PMID 41134056, 2025). "Therefore, we propose that CEP290 might be considered as a causal and modifier gene in motile ciliopathies." (PMID 38534367, 2024). "Although it remains to be determined how this mechanism is triggered and what the role of genetic background may be in this process, our findings constitute a new genetic compensation mechanism in ciliopathy that will further our understanding of genotype-phenotype discrepancies in cep290 mutations." (PMID 34155518, 2021). "Similar oligogenic contributions have been suggested in other ciliopathies, including cases with CEP290." (PMID 40500351, 2025). "CEP290-related ciliopathies arise from molecular dysfunctions of the CEP290 molecule, exhibiting a diverse range of symptoms." (PMID 40632733, 2025). "Given the importance of this gene for the spectrum of ciliopathies, a broad variety of functions has been assigned to CEP290, which makes it challenging to identify its predominant role in the CNS." (PMID 41064933, 2025). "Two individuals (3.6%, 2/55) carried variants in CEP290, known for its role in non-syndromic IRD or syndromic ciliopathies with IRD." (PMID 38892339, 2024). "This study shows that the Cep131-Cep162 module near the axoneme and the Cby-Fam92 module near the membrane work together to regulate the localization of the highly conserved ciliopathy protein Cep290 at the basal body to initiate ciliogenesis." (PMID 38442096, 2024).
ciliopathies (continued). "Whilst suitable for a number of ciliopathy-related genes, such as RPGR (3.5 kb), many genes are beyond this capacity, including CEP290 (7.4 kb) and several of the Usher-syndrome-associated genes (MYO7A: 6.6 kb, CDH23: 10 kb, ADGRV1: 18.9 kb, USH2A: 15.6 kb)." (PMID 38474133, 2024). "A proteomic analysis of purified TZs from Chlamydomonas identified 115 distinct proteins, several of which are known to be mutated in human ciliopathies 11, including components of the three main TZ protein modules, the MKS, NPHP and CEP290 modules 2,12–14." (PMID 37072495, 2023). "Eupatilin was suggested to exert its effect on CEP290 ciliopathy at the protein level through calmodulin binding and release of NPHP5 to the transition zone." (PMID 37371046, 2023). "This strengthened confidence that the molecular diagnosis is correct and that this participant is highly likely to have a CEP290-related syndromic ciliopathy." (PMID 35764379, 2022). "Further, Cep290 localization reflects its function as only cells in which Cep290 is localized specifically to pericentriolar satellites show mutant and knockdown ciliopathy phenotypes." (PMID 34155518, 2021). "In a separate report, morpholino-induced knockdown of cep290 in zebrafish also prevented photoreceptor outer segment formation and other ciliopathy defects." (PMID 30970040, 2019). "The clinical phenotype of CEP290 mutations, as with that of other JBTS and related ciliopathy genes, consists of a broad spectrum." (PMID 28973549, 2017). "CEP290, a component of the RGRIP1 protein complex and a ciliopathy-causing gene, is also required for Rab8 primary cilium localization." (PMID 29203866, 2017). "Cep290 is one of eleven ciliopathy genes that include cc2d2a and involve retinal dystrophy as well as other defects, such as polycystic kidney." (PMID 23351173, 2012). "We have specifically focused on two ciliary proteins – CEP290 and RPGR – that underlie photoreceptor degeneration and syndromic ciliopathies." (PMID 23351659, 2012). "In this review we have discussed differences between human ciliopathies and their respective mouse models, focusing on CEP290, RPGR and their interactors." (PMID 23351659, 2012). "Several subtypes of LCA can be considered part of the ciliopathies, as four disease genes – TULP1, RPGRIP1, CEP290 and LCA5 – encode ciliary proteins." (PMID 20683928, 2010). "Our results reveal that the first step of ciliogenesis strictly depends on cooperative and retroactive interactions between Cep131-Cep162, Cby-Fam92 and Cep290, which may contribute to the complex pathogenesis of Cep290-related ciliopathies." (PMID 38442096, 2024). "Therefore, identification of the modifier genes has become an important element to understand the pathogenesis of Cep290-related ciliopathies." (PMID 38442096, 2024). "In patients with a variety of syndromic ciliopathies attributed to variants in NPHP3, IQCB1, CEP290, and MKS1, a common RPGRIP1L variant (p.Arg229Thr) (present in over 8% of South Asians and 3% of other populations) is significantly enriched in patients who also have retinitis pigmentosa." (PMID 37628633, 2023). "However, the precise function of each domain of CEP290 in cilium assembly and mechanisms of distinct CEP290-ciliopathies require further investigation." (PMID 32747192, 2021). "Compared to strong ciliopathy phenotypes in acute cep290 knockdown zebrafish, the results indicate that an adaptive compensation mechanism may suppress a genetic mutant phenotype." (PMID 34155518, 2021). "The evolutionarily conserved TZ component centrosomal protein 290 (CEP290) is the most frequently mutated human ciliopathy gene, but its roles in ciliogenesis are not completely understood." (PMID 33370260, 2020). "Due to all these data and since the TZ amount of Cep290 was reduced in all analysed Rpgrip1l−/− mouse cell types, Cep290 might be an important factor in the development of the very severe ciliopathy of Rpgrip1l−/− mouse embryos." (PMID 29650680, 2018).
ciliopathies (continued). "CEP290 mutations have not been directly related to cell cycle defects, although a related ciliopathy gene CEP164 (alias NPHP15) regulates cell cycle progression and is implicated in DNA damage response signaling." (PMID 28973549, 2017). "However, the positive response of both Cep290 and Nek8 mutant cells (and other ciliopathy models ) to CDK inhibitors suggests a common aetiology." (PMID 28973549, 2017). "In addition, recent studies have shown that the USH interactome is molecularly linked to other proteins whose mutations lead to ciliopathies, including RPGR and CEP290." (PMID 26881841, 2016). "Besides Cep290 and NPHP5, two other ciliopathy-associated proteins, MKS1 and MKS3, are also required for the translocation of centrioles to the cell surface, whereas IFT88 is not." (PMID 24053599, 2013). "Gene knockdown of the centrosomal protein Cep290 resulted in zebrafish with visual defects and other symptoms of ciliopathies similar to those seen in Leber's congenital amaurosis, Meckel-Gruber syndrome, Joubert syndrome, Senor-Loken syndrome and Bardet-Bledl syndrome." (PMID 23351173, 2012). "Pharmacological treatments for human CEP290 ciliopathies are still lacking and therefore we aimed to explore potential drug treatments using human urine-derived renal epithelial cells (hURECs) from patients with CEP290 mutations." (PMID 28973549, 2017). "Our recent discovery that C. elegans TMEM-17 is an MKS module protein that depends on CEP-290 for TZ localisation suggests that it may also be linked to one or more ciliopathies; however, such a possibility has not been reported." (PMID 26982032, 2016). "The study found that SPAG6, TRAF3IP1, IFT22, and KIF3B showed lower correlations with ciliopathies, while IFT172, TTC21B, CEP290, ACTB, and DYNC1H1 were highly correlated." (PMID 40432967, 2025). "In addition to LCA, CEP290 is associated with Joubert syndrome (JS; MIM# 213300), Senior-Loken syndrome (SLS; MIM# 266900), Meckel-Grüber syndrome (MKS; MIM# 249000) and Bardet-Biedl syndrome (BBS; MIM# 209900); a range of clinically and genetically heterogeneous ciliopathies." (PMID 20683928, 2010). "Our results also suggest that not all ciliopathy genes are absolutely essential for ciliogenesis, and that for the relatively large CEP290 gene, expressing small GTPases in affected tissues may be an alternative and more feasible route to gene therapy for human CEP290 mutations." (PMID 34155518, 2021). "Furthermore, the centrosomal protein CEP290, mutated in a range of ciliopathies including Joubert syndrome, has also been implicated in the regulation of DNA replication stress and DDR, suggesting that chronic replication stress may be a key driver in the development of some ciliopathies." (PMID 27335639, 2016). "Some ciliopathy proteins, such as BBS4, CEP290 and OFD1, are constituents of centriolar satellites." (PMID 23110211, 2012). "Our current knowledge of CEP290 is predominantly based on studies in Chlamydomonas, specialized cell types, such as photoreceptors or kidney tubule cells in mouse, cell lines (e.g. hTERT-RPE1, IMCD3) and human fibroblasts or urine epithelial cells (hURECS) derived from individuals with ciliopathies." (PMID 41064933, 2025). "In preliminary experiments, we found no defects in cilia structure or protein localization in zebrafish cep290 and bbs4 Crispr/Cas9 mutants (data not shown) suggesting that for some ciliopathy genes, compensation mechanisms may mask ciliopathy phenotypes." (PMID 29568513, 2018).